NECTIN2 (nectin cell adhesion molecule 2)
Diseases named in the same sentence as NECTIN2 in open-access papers (continued):
Sharing a sentence is not in itself a finding about the gene and the disease.
cancer (continued). "TIGIT and CD226 are paired receptors that compete for shared ligands CD155 (PVR) and CD112 (Nectin-2) expressed by cancer and antigen-presenting cells." (PMID 30400822, 2018). "In order to investigate the potential of Nectin-2 as a target for antibody therapies of cancers, we generated anti-Nectin-2 rabbit poAb using recombinant Nectin-2 protein as an immunogen." (PMID 23758976, 2013). "We also investigated the potential of this molecule as a target for antibody therapeutics to treat cancers by generating and characterizing an anti-Nectin-2 rabbit polyclonal antibody (poAb) and 256 fully human anti-Nectin-2 monoclonal antibodies (mAbs)." (PMID 23758976, 2013). "To determine the expression of Nectin-2 in cancer tissues and cancer cell lines, we performed gene expression profile analysis, immunohistochemistry studies, and flow cytometry analysis." (PMID 23758976, 2013). "SS assessed the mRNA and protein expression levels of Nectin-2, and performed the cancer cell proliferation and CDC assay." (PMID 23758976, 2013). "The anti-Nectin-2 mAbs demonstrated antibody-dependent cellular cytotoxicity (ADCC) and epitope bin-dependent features such as the inhibition of Nectin-2-Nectin-2 interaction, Nectin-2-Nectin-3 interaction, and in vitro cancer cell proliferation." (PMID 23758976, 2013). "TO generated anti-Nectin-2 mAbs and executed Nectin-2-Nectin-2 and Nectin-2-Nectin-3 interaction assays and the cancer cell proliferation assay." (PMID 23758976, 2013). "We found that high expression of PVR and NECTIN2 predicts poor prognosis in a variety of cancers." (PMID 39120585, 2024). "NECTIN2 also gives new expectations in cancers such as HCC, BRCA, PRAD." (PMID 39120585, 2024). "Their results showed high expression of nectin-2 in all cancer samples." (PMID 37568798, 2023). "The expression of nectin-2 was significantly higher in the cancer tissue than the healthy mucosa." (PMID 37568798, 2023). "However, there have been few reports on the roles of nectin-1, nectin-2, and nectin-3 in cancer development and prognosis." (PMID 36059705, 2022). "Immune-checkpoint inhibitors targeting the PVRIG-Nectin-2 axis in Nectin-2 positive cancers may be evaluated as potential drugs." (PMID 36553083, 2022). "Therefore, we decided to generate anti-Nectin-2 mAbs to further evaluate the potential of antibody therapy to treat Nectin-2 over-expressing cancers." (PMID 23758976, 2013). "With the aim of identifying target proteins for antibody therapeutics, we searched for membrane-bound proteins that were over-expressed in cancer tissues compared to normal tissues using Affymetrix GeneChip Technology and found that Nectin-2 mRNA was over-expressed in various cancer tissues." (PMID 23758976, 2013). "Nectin-2 was over-expressed in various cancer cell lines as well." (PMID 23758976, 2013). "The authors further determined that Nectin-2 was over-expressed in various breast and ovarian cell lines using flow cytometry, concluding that Nectin-2 could serve as a target for antibody therapy in these cancer types." (PMID 24386110, 2013). "It binds to CD155 and CD112 (nectin-2) present on cancer cells surface and endothelial cells and may be important for extravasation of NK cells." (PMID 22547986, 2012). "Finally, we checked for the effect of TAK-981 on (i) TIGIT (inhibitory receptor) and DNAM1 (activating receptor), which compete for binding to PVR and Nectin-2 on cancer cells, and (i) LFA1, which binds to ICAM-1 and stabilizes NK interaction with their target cells." (PMID 40661051, 2026). "Notably, we identified several key ligand-receptor pairs in TNChigh cancer cells and immune cells, including NECTIN2-TIGIT, MIF-(CD74+CD44), MDK-NCL, LAMB3-CD44, COL1A2-CD44, COL1A1-CD44, CD99-CD99, APP-CD74, and GZMB-PARD3 were identified in TNChigh cancer cells and immune cells." (PMID 38711034, 2024). "Besides, the TIGIT- NECTIN2 interaction between T cells and cancer cells was found in MBC samples." (PMID 37696831, 2023).
cancer (continued). "Thus, Nectin-2 was shown to be a promising target for antibody-based cancer therapies." (PMID 23758976, 2013). "However, little has been reported about the involvement of Nectin-2 in cancer." (PMID 23758976, 2013). "The engagement of TIGIT with its binding partners, poliovirus receptor (PVR) (CD155), nectin-2 (CD112), and nectin-4 (PVRL4)—plays a pivotal role in modulating immune reactions and the evolution of cancer." (PMID 40777027, 2025). "Poorly differentiated cancers, tumors infiltrating surrounding tissues, cancers with metastasis to lymph nodes and TNM III and IV were identified as having higher percentages of nectin-2 expression." (PMID 37568798, 2023). "In the present study, our analysis has shown that CD276 expression was positively correlated with a number of immune checkpoint genes, including TGFBR1, TGFB1, NECTIN2, IL10RB and CSF1R, in most types of cancer." (PMID 36717836, 2023). "Other immune checkpoint ligands, NECTIN2, LGALS3, and LGALS9 were highly expressed in cancer cells or other infiltrating cells." (PMID 36529697, 2023). "Other immune checkpoint ligands, such as NECTIN2, LGALS3, LGALS9, and SELPLG, were highly expressed in cancer cells or other infiltrating immune/stromal cells." (PMID 36529697, 2023). "DNAM-1 binds to CD112 (also known as nectin 2) and CD155 (also known as the poliovirus receptor, PVR), which is improperly expressed in cancer cells." (PMID 34439285, 2021). "TIGIT binds to three ligands, namely CD155 (PVR), CD112 (Nectin-2), and CD113 (Nectin-3), that are expressed on APCs and cancer cells." (PMID 34948104, 2021). "Our expression analysis indicated that NECTIN2 was expressed in A549 cancer cells but not in T cells." (PMID 40371640, 2025). "On the other hand, the expression of nectin-2 in cancers such as colorectal cancer and bladder cancer does not have any clinical significance." (PMID 40244005, 2025). "We find that cancer cells release blebbisomes containing an abundance of immune evasion and inhibitory immune checkpoint proteins, including PD-L1, PD-L2, B7-H3, VISTA, PVR, Nectin-2, HLA-E, CD73 and CD47." (PMID 39984653, 2025). "We found that cancer-cell-derived blebbisomes express not only PD-L1 but also a plethora of other inhibitory ligands, including PD-L2, B7-H3 (CD276), VISTA (B7-H5), HLA-E, PVR (CD155) and Nectin-2 (CD112)." (PMID 39984653, 2025). "Although we found that Nectin-2 was over-expressed in various types of cancers, there has been no report suggesting the involvement of Nectin-2 in cancer cell proliferation." (PMID 23758976, 2013). "However, there are still many cancers for which there are no reports regarding the presence and impact of nectin-2 expression on their development." (PMID 40244005, 2025). "Similarly, ZNF668 was positively correlated with PVRL2 (Nectin-2), CD276 (B7-H3), TGFB1, and multiple members of the TNF receptor superfamily, including TNFRSF4 (OX40), TNFRSF18 (GITR), and TNFRSF25, in the vast majority of analyzed cancers." (PMID 41614761, 2025). "Lastly, both Nectin-2 and Nectin-4 were not specific to the cancer tissues, which could impact on the results of this study." (PMID 37174031, 2023).
infection (27 papers, 2006 to 2025). The state of being infected such as from the introduction of a foreign agent such as serum, vaccine, antigenic substance or organism. "In this study, Oki53 and Oki65 infection induced nectin-2 displacement from the membrane and afadin degradation in RPTECs." (PMID 41187201, 2025). "Surprisingly, we were not able to demonstrate an increase in expression of the two main ligands for DNAM-1, CD155 (the Polio Virus Receptor/Nectin-like protein 5) and CD112 (Nectin-2), by flow cytometry following either dl922-947 or enadenotucirev infection." (PMID 32195317, 2020). "Infection with Nectin-2 shRNA lentivirus significantly reduced Nectin-2 mRNA expression levels to 22±2% and 18±5% in the two OEC lines." (PMID 27676263, 2016). "Nectin-2 is considered a low efficiency receptor; therefore, cells expressing nectin-2 requires high multiplicity of infection in order to be infected." (PMID 22029482, 2011). "Additionally, HHV-6B gB has been reported to interact with nectin cell adhesion molecule 2 (nectin-2) to facilitate the infection of salivary gland cells that lack CD134." (PMID 40632757, 2025). "As salivary gland cells are also permissive for HHV-6A, it remains to be investigated whether HHV-6A also utilizes nectin-2 for infection." (PMID 40632757, 2025). "We hypothesize that HHV-6B infection of salivary glands in vivo can be explained by two molecules, nectin-2 and CD134." (PMID 35062364, 2022). "Furthermore, in addition of cell adhesion functions, Nectin-2 mediates both entry and spreading of infection from various viruses and has also been reported that DNAM-1 (CD226) and TIGIT interact Nectin-2 to activate immune cells." (PMID 29723247, 2018). "Thus, the high activity of nectin‐2 in patients with COVID‐19 is primarily a response to the initial infection, but overactivity may ultimately stunt long‐term natural killer cell effectiveness." (PMID 40476695, 2025). "HHV-6B gB has been reported to interact with nectin-2, which can serve as an alternative receptor in cells lacking the gH/gL/gQ1/gQ2 tetramer receptor CD134, thus mediating infection." (PMID 40632757, 2025). "In the present study, E-cadherin, α-catenin, and Nectin-2 were displaced from the cell membrane upon infection, but their protein levels were not decreased in whole-cell lysates." (PMID 41187201, 2025). "For NECTIN2 knock-down, however, despite of the multiple experiments by using shRNAs (four different shRNAs) with multiplicity of infection 1 and 2, none of them led to consistent and robust reduction in NECTIN2 protein levels in our cell model." (PMID 38172904, 2024). "HSV-1 uses several routes of entry to initiate infection of cells including HVEM (TNFRSF14), nectin-1, nectin-2, 3-O-sulfated heparan sulfate (3-OS-HS), paired immunoglobulin-like type 2 receptor (PILRα), non-muscle myosin heavy chain IIA (NMHC-IIA), and myelin-associated glycoprotein (MAG)." (PMID 37738264, 2023). "- Cells expressing Nectin-2 need more HSV particles than Nectin-1 for infection.- Nectin-1 or -2 can mediate HSV-2 entry, but wide-type HSV-1 can interact with nectin-1 only.- The amino acid sequence of Nectin-1 is 30% different from Nectin-2." (PMID 38076455, 2023). "The presence of nectin-2 did not enhance MP infection above the CHO cell background, but instead reduced the plating efficiency for reasons that are not clear." (PMID 17192179, 2006). "PVR (CD155) and Nectin-2 (CD112), ligands for DNAM-1, were highly expressed but not modulated by infection." (PMID 36341337, 2022). "However, nectin-2, that shares 30% homology with nectin-1 at the protein level, serves as a receptor only for HSV-2 and some unrestricted HSV-1 mutants that do not exhibit gD-mediated restriction of infection." (PMID 22029482, 2011).
adenocarcinoma (3 papers, 2015 to 2023). A common cancer characterized by the presence of malignant glandular cells. "Nectin-2 and nectin-4 were also expressed in the membranes and cytoplasm of the adenocarcinoma cells, although the degree of expression was usually weak." (PMID 25690753, 2015).
cardiovascular disease (2 papers, 2021 to 2024). "Based on the DEG between IS etiologies and its association with cardiovascular diseases in previous studies, we selected three over-represented genes in EVs for further validation; namely, IGFBP-2 and PECAM-1 increased in EVs from CE patients, and NECTIN-2 overexpressed in AT patients." (PMID 38673963, 2024).
hematologic cancers (2 papers, 2022 to 2024). "Meanwhile, TIGIT recognizes poliovirus receptor (PVR or CD155), Nectin-2 (CD112), or Nectin-3 overexpressed in hematologic cancers." (PMID 35990652, 2022).
CNS tumor (1 paper, 2021). "For brain and CNS tumor samples, CADM1, CADM2, NECTIN1, and NECTIN3 were downregulated, whereas NECTIN2 was overexpressed." (PMID 34925438, 2021).
NECTIN2 also shares sentences with these, for which no sentence is quoted: dyslipidemia (7 papers); gastric cancer (4); liver cancer (4); multiple sclerosis (4); myeloma (4); sarcoma (3); angina pectoris (2); asthma (2); atherosclerotic heart disease (2); autoimmune disease (2); cervical cancer (2); endometrial carcinoma (2); preeclampsia (2); type 2 diabetes (2); adenocarcinoma of the gallbladder (1); adenosquamous carcinoma (1); Autoimmunity (1); B-cell acute lymphoblastic leukemia (1); brain diseases (1); chronic pancreatitis (1); cleft lip (1); cleft lip and palate (1); colitis (1); Creutzfeldt Jakob disease (1); depression (1); endometrial tumor (1); familial Alzheimer disease (1); fibrosarcoma (1); gout (1); gynecological cancers (1).
A further 21 diseases each share a sentence with NECTIN2 in 1 paper.